CD4 (CD4 molecule)
Diseases named in the same sentence as CD4 in open-access papers (continued):
Sharing a sentence is not in itself a finding about the gene and the disease.
tumor (continued). "In mouse tumors, the systemic inhibition of ROCK hindered tumor progression by decreasing the expression of tumor-derived PD-L1, which in turn resulted in increased infiltration of CD4+ and CD8+ T cells." (PMID 39507618, 2024). "In relation to CD4+ T lymphocytes, these cells also present an exhausted phenotype in different tumor types and, most likely, undergo modifications evoked by ICB, that in turn affect the antitumor immune response." (PMID 38690280, 2024). "Fucosan can inhibit the tumour cell migration that is induced by the M2 macrophage conditioned medium, the function of CD4+ T lymphocytes, and especially the recruitment of Tregs by inhibiting CCL22 via the activity of NF-κB, which reduces CCL22 production." (PMID 38475858, 2024). "This study thus not only documents a new function for a known CD4+ T cell subpopulation but also provides a strategy to circumvent their inhibitory effects on tumour rejection." (PMID 39048822, 2024). "To better understand how C-100 (growing) and C-225 (eradicated) elicited opposite outcomes of anti-tumor immunity, we performed flow cytometry analysis to characterize CD4 and CD8 TILs in the TME." (PMID 39055715, 2024). "Tumor cell-derived MIF promotes expansion of Tregs (consistent with the IL-2 ARP we observed in CD4+ T cells via ASPEN) and inhibits CD8+ T cell activation." (PMID 39483921, 2024). "Similar to the homeostatic conditions, tumor-bearing CD11c:DTA mice showed a reduced proportion of CD4+Foxp3+ Treg cells and an enhanced proportion of CD4+Foxp3+RORγt+ Treg cells in TdLNs and Spl as compared with tumor-bearing WT mice." (PMID 39206204, 2024). "Conversely, reductions in Tfh cell populations result in compromised TLS, diminished immune infiltration, and weakened tumor control; however, these features can be restored following the transfer of pathogen-specific CD4+ T cells." (PMID 39026670, 2024). "It plays a crucial role in facilitating the secretion of cGAS-STING1-dependent type I interferons, which have an important role in the differentiation of both CD8+T cells, CD4+T cells and NK+ cells, as well as in immune-mediated suppression of tumour growth." (PMID 39723259, 2024). "Considerable proportions of M2 macrophages, monocytes, and resting memory CD4 + T cells were detected in the tumor group." (PMID 38173044, 2024). "Spatially resolved maps reveal cellular neighborhoods recapitulating functional units of the tumor ecosystem and the spatial proximity of B and CD4+ T cells at immunogenic sites." (PMID 38682485, 2024). "There was an increase in CD3 and CD4 cell infiltrates in omental tumours post-NACT (eight PDS and twenty-three NACT patients) but this was statistically significant only for CD3 cells." (PMID 39578450, 2024). "This approach was used to assess the cells collected from tumor tissues and measure CD4 and Foxp3 expression using flow cytometry, where the aCD20@ExoCTX/siPDK4 group significantly inhibited the activity of Treg cells in tumor tissues compared to other groups." (PMID 39004737, 2024). "In a pancancer meta-analysis of 21 different tumor types, scRNAseq data revealed intratumoral CD4+ T cells as two main populations: Tregs and conventional T cells that are of an undecided T follicular helper (Tfh)/Th1 phenotype." (PMID 38383773, 2024). "CD8 T cells stand as principal effector cells in anti‐tumour immunity, whereas CD4 T cells play an irreplaceable role in preserving the anti‐tumour properties of CD8 T cells." (PMID 38429900, 2024). "All of these data together suggest that the increased DC phenotype observed also directly impacts the CD4+ T cell compartment, which results in a microenvironment that is tumor supportive." (PMID 38495876, 2024). "We found that the majority of circulating CD4+ T factors had correlating factors in the NMF defined by the CD4+ tumor-infiltrating lymphocyte (TIL) data." (PMID 38359792, 2024).
tumor (continued). "We report that galectin 7 reduced CD4+ T cell percentage in both in vitro culture and mouse tumor models." (PMID 38503797, 2024). "Most immune cells were significantly decreased in TCGA LUAD tumor tissues with high TIMELESS expression except for CD4+T cells and Th2 cells." (PMID 38261568, 2024). "Collectively, our data suggest that PRMT3 inhibition activated the anti-tumor immunity through increasing CD4+ and CD8+ T cell infiltration and activating CD8+ T cells." (PMID 39256398, 2024). "The level of miR-21 expression was significantly higher in CD4 (+) tumor cells found in the peripheral blood of SS patients." (PMID 39256366, 2024). "The injection of an AAV vector containing the CD4 targeting CAR gene allowing for the generation of potent CAR T cells in vivo that ultimately led to tumor regression in a mouse model." (PMID 39835140, 2024). "One of these agents, bortezomib, inhibits the numbers and functions of activated normal naïve B, memory B, plasma cells, and CD4 T cells, whereas it increases regulatory T cell numbers and enhances NK cell-mediated anti-tumor responses." (PMID 38348048, 2024). "Activated SWHEL B cells were co-transferred with naïve CFSE labeled 5C.C7 CD4+ T cells into I-E- tumour bearing hosts." (PMID 38125720, 2024). "Tumor rejection correlated with rapid and sustained infiltration of myeloid and particularly lymphoid cells of both CD4 + and CD8 + subtype, strongly indicating the immunological nature of rejection." (PMID 39334370, 2024). "The significant increase in CD4 T cells post-treatment emphasized a critical role of CD4 T cell compartment in tumor control." (PMID 38280003, 2024). "Among the core genes, PRSS16, encoding a thymus-specific serine protease (TSSP), which is involved in CD4+ T-cell maturation in the thymus, has tumor suppressor activity." (PMID 39600695, 2024). "The depletion of CAFs and the elimination of leaky tumor angiogenic vessels by ProAgio alter tumor immunity as revealed by an increase in CD8+ T-cells and decreases in CD4+ Treg and MDSCs in the tumor." (PMID 39001545, 2024). "CD4+ T lymphocytes produce several inflammatory cytokines that can elicit a vigorous anti-tumor immune response." (PMID 38164359, 2024). "RACIM led to increased infiltration of tumour-specific activated effector CD4+ and CD8+ T cells expressing IFN-γ, granzyme B, and perforin." (PMID 38833685, 2024). "To verify the incited inflammatory response driven by tumor–T cell interactions, we performed functional co-culture assays for CD4+T cells and OPSCC tumor cells." (PMID 39105803, 2024). "The immune cells, comprising mostly CD8+ T cells and CD4+ T cells, B cells, and NK cells have been found outside of the tumor ‘nest’." (PMID 39605357, 2024). "The results also indicate that the direct effect on either CD4+ or CD8+ T cells alone is sufficient to reduce tumor growth." (PMID 39474427, 2024). "CD8+ and CD4+ effector cells and regulatory T cells from urine precisely signaled the immune response of the body and provided a map of the tumor microenvironment (TME), which offers researchers the potential to determine the tumor’s stage and status." (PMID 38398192, 2024). "Numerous studies indicate that CD4+ T cells, a major T lymphocyte subpopulation, play a crucial role in tumor immunity and exhibit diverse functions." (PMID 38292868, 2024). "Cytotoxic CD8+ T cells and CD4+ T helper (Th) cells can eliminate pathogens and tumor cells, but their autoreactive counterparts mediate autoimmune tissue damage." (PMID 39211051, 2024). "Treatment delayed tumor growth, while also inhibiting lung metastasis, reducing splenomegaly, increasing activated IFNγ+ CD4+ and CD8+ splenocytes, and increasing tumor infiltrating CD8+ T cells." (PMID 38803496, 2024). "For example, the significantly improved clinical prognosis of patients with proficient mismatch repair (pMMR) CRC is correlated with the extent of CD4+GzmB+ T-cell infiltration in the center of the tumor." (PMID 38515134, 2024).
tumor (continued). "Stratifying regions by MSH6 labeling revealed a clear increase in infiltrating CD8-positive cytotoxic T cells, CD20-positive B cells, CD4-positive T cells and FoxP3-positive Treg cells in MSH6-deficient tumor regions." (PMID 38956208, 2024). "We found that compared with the treatment by ICIs alone or HLJD alone, HLJD combined with ICIs significantly increased the tumor infiltration of DCs, CD4+T and CD8+T cells." (PMID 38605368, 2024). "Andrographolide, the main active compound in Andrographis Herba, regulates tumor tissue growth factors, suppresses tumor development, induces tumor cell death, and enhances infiltration and activity of CD4+ and CD8+ T lymphocytes." (PMID 39660124, 2024). "Treatment delayed tumor growth, associated with an increase in CD4+ and CD8+ T cells and a decrease in Tregs, CD11b+ MDSCs and CD206+ M2 macrophages in the tumor." (PMID 38803496, 2024). "CD4+ T cells enhance tumor antigen presentation through interactions with antigen-presenting cells like dendritic cells, thereby boosting the cytotoxic activity of CD8+ T cells." (PMID 39493764, 2024). "These cells attract CD4+ regulatory T cells, known for their immunosuppressive effects, further dampening immune responses against the tumor." (PMID 39215399, 2024). "With this review, we highlight the role of tissue specific CD4+ T lymphocytes in homeostasis and also in tumor establishment/development across different organs." (PMID 38690280, 2024). "The intrinsic sensitivity of IFN-γ to the pro-apoptotic effects of tumors is an important determinant of the anti-tumor activity of CD4+ CAR-T cells." (PMID 39464890, 2024). "Within tumour CD4+ Treg cells, IgG2b and IgG2a anti-TIGIT antibodies reduced the expression of genes associated with suppressive capacity, including Tigit, Ccr8 and Ctla4." (PMID 38418879, 2024). "IL-10 secreted by Bregs suppresses the activity of cytotoxic CD8+ T cells, Th1 and Th17, and induces the conversion of CD4+ T cells to Tregs, thereby promoting tumor immune evasion." (PMID 39085965, 2024). "Distinct immune landscapes were identified, revealing an increased presence of CD8+ T cells and a decreased CD4+ T cell fraction within the tumor microenvironment." (PMID 38672617, 2024). "Analysis of the immune response in tumour-draining lymph nodes showed that the percentage of CD4+IFNγ+ cells was significantly higher in anti-IL-33 treated mice." (PMID 38662248, 2024). "We tested the protein expression of some of these genes and others associated with T and NK cell cytotoxicity (CD4, CD8, IFN-γ, Perforin 1, and NKp46) via immunofluorescence imaging within the tumor sections." (PMID 39703517, 2024). "More tumor-infiltrating CD4+ T cells exhibited the cluster 3 and cluster 5 phenotypes in MMRd tumors than in MMRp tumors." (PMID 38383773, 2024). "CD4+T cells, as the hub of the immune system, secrete cytokines with anti-tumor effects and activate other immune effector cells." (PMID 38263363, 2024). "Unsupervised clustering of the scRNA-seq data revealed transcriptionally distinct subsets, with 9 and 10 clusters in SILP and B16-3340 tumor, respectively, each expressing known markers of different CD4+ T cell subsets." (PMID 39185202, 2024). "Tumor-specific CD8 + T cells are the core cells in the TME that exert antitumor effects, and CD4 + T cells can be used as an important prognostic factor for the immune response of the tumor microenvironment." (PMID 38254043, 2024). "PGE2 also reduces the expression of cytokines, i.e., INF-γ and IL-4, shifting the immune balance towards Th2 cells; in this way, it contributes to an increase in anti-tumour activity by promoting immunosuppressive cells such as regulatory CD4+CD8+FoxP3+ Tregs." (PMID 39120301, 2024). "E. coli TOP10 induces the activation of CD8+ and CD4+, which are the effector cells to inhibit tumor occurrence and progression." (PMID 38273292, 2024). "Our objective is to generate CAR T cells that will eliminate these CD4 + T cells from the tumor tissue." (PMID 39272178, 2024).
tumor (continued). "Since NK cells can express CTLA4 and CD2548,49, we utilized anti-OX40 Abs, which efficiently deleted the FoxP3+ CD4 T cells within the tumor while leaving NK cells intact." (PMID 38267402, 2024). "Once dendritic cells (DCs) recognize and up-take these tumor antigens, they migrate to neighboring lymph nodes where they present tumor antigens to naïve CD4+ and CD8+ T cells." (PMID 39081320, 2024). "Treatment with the anti‐PD‐L1 inhibitor showed a marked increase in CD8+ and CD4+ T‐cell infiltration inside the tumor, indicating an immunogenic microenvironment." (PMID 38511232, 2024). "The infiltrate persisted with the addition of a MEK inhibitor (trametinib) to dabrafenib, which was also associated with an increase in CD4+, CD8+ and PD-1+ T cells, as well as in programmed death-ligand 1 (PD-L1) expression on tumor cells." (PMID 38907159, 2024). "Along with CD8 T cells we can identify CD4 T cells that have migrated from the tumor to the TdLN and a significant population of CD8−CD4− T cells that have been identified as gamma delta T cells." (PMID 38789721, 2024). "TLs are divided into CD8+ cytotoxic and CD4+ helper cells, with several subtypes having either anti-tumor or pro-tumor effects." (PMID 39765634, 2024). "In mice, CD40 agonism can mediate tumor clearance via stromal remodeling, induction of tumoricidal macrophages, and activation of CD4+ and CD8+ T cells." (PMID 38181044, 2024). "Secondly, anlotinib can promote the normalization of tumor vasculature through CD4+ T cells, transforming the immunosuppressive tumor microenvironment into an immunostimulatory one, inhibiting tumor growth, and preventing systemic immunosuppression." (PMID 39723389, 2024). "Meanwhile, mIHC staining showed that tumor‐infiltrating CD4+ T cells, CD8+ T cells and CD20+ B cells outside the TLS zone were higher in patients with a high TLS density than in those with a low TLS density; however, the infiltration of CD15+ TANs was low." (PMID 38322490, 2024). "Although there are various subtypes of CD4 + T cells, these cells have different and even opposing effects that suppress or stimulate tumor development." (PMID 38468248, 2024). "Blocking IL-4, which suppresses IL-12 production, in NSCLC mouse models augmented cytokine production by CD4+ T cells activated by mregDCs, resulting in reduced tumor growth and an increased expansion of IFNγ+TNF+CD8+ T cells." (PMID 38716077, 2024). "This enabled us to extrapolate transendothelial migration from ratios of CD4+ T cells in the tumor versus in the vessels." (PMID 39091728, 2024). "Among the components of the tumor immune microenvironment, the degrees of CD4 + cell and CD163 + cell infiltration and IL-6 expression in cancer tissues were significantly correlated with FDG PET/CT imaging features of primary tumors." (PMID 38627864, 2024). "In the tumor environment, due to the secretion of H-ferritin, cytokines, and chemokines, regulatory CD4+ T cells accumulate." (PMID 39519055, 2024). "In our study, CCR5 antagonism enhanced anti-tumour effector T cell function by increasing IFN-γ production by CD4+ T cells, which plays an important role in mediating tumour regression." (PMID 38672174, 2024). "Expression levels of CD68, representing all TAMs, and of CD4 were consistently and highly expressed throughout all stages of tumor progression, whereas CD8A expression was increased in later disease stages." (PMID 38618956, 2024). "For example, augmented radiation-induced tumor growth delay by TGF-β neutralizing antibody is completely abated by CD8+ or CD4+ T cell depletion, implicating the requirement of cytolytic T cells for improved radiation therapeutic efficacy." (PMID 38912586, 2024). "In contrast, the observed decreased CD4+ T cell fraction raises questions about tumor-mediated immune alterations." (PMID 38672617, 2024). "HLJD increased the tumor infiltration of anti-tumor immune cells, especially DCs, CD4+ T cells and CD8+T cells." (PMID 38605368, 2024).
tumor (continued). "They found that CXCL13+PD-1+ CD4+ T cells (equal to CD4.c16/17) augmented antitumor cytotoxicity through interaction with LAMP3+ DCs in tumor-draining lymph nodes (TDLNs)." (PMID 38343549, 2024). "As a USP1 inhibitor, ML323 reduces macrophage infiltration, regulates CD4+ T cell differentiation, and inhibits Th17 cell development, maintaining immune balance and exerting anti-tumor effects." (PMID 39868366, 2024). "There was also a significant difference in the tumor volume and tumor growth rate among the DMBA-treated mice versus the CD4-depleted DMBA-treated mice (p-value = 0.0218)." (PMID 39339897, 2024). "Tumor-specific CD4 T cells instructed MHC class II-expressing monocytes to differentiate into anti-tumor macrophages." (PMID 39315092, 2024). "Tumor specific MHC-II expression is important for immune surveillance and tumor cell recognition via CD4+ TCR engagement of class II-restricted antigens and plays a role in immunotherapy response." (PMID 38822345, 2024). "Unexpectedly, the typical CD8+ T cell states were unchanged in tumor and normal tissues, while cytotoxic CD4+ T cells showed the opposite." (PMID 39334490, 2024). "The proportions of Macrophages M2, CD4+ memory resting T cells, Eosinophils, Monocytes, and Neutrophils were comparatively high in SP-EP tumor tissue, whereas the proportions of other immune cell types were relatively low." (PMID 39346772, 2024). "For instance, memory CD4+ T cells, regulatory T cells, NK cells and dendritic cells have been suggested as prognostic tumor-infiltrating immune cells for EC patients." (PMID 39668821, 2024). "Cytotoxic effect on tumor cells of three populations of lymphocytes was studied: NK cells, CD4+ and CD8+T lymphocytes." (PMID 38203798, 2024). "Activation of plasmacytoid dendritic cells (pDCs); induction of CD8+ T cell responses via TLR9 in a CD4+ T cell-independent manner; remission of tumor." (PMID 38983849, 2024). "Loss of MHC class I and/or β2M as well as loss of MHC class II can lead to immune escape, with the former by inducing the immune escape of CD8+ Tumor Infiltrating Lymphocytes (TILs), and the latter by protect the body from CD4+ TIL." (PMID 39240588, 2024). "HSP60-KD reduced tumor volumes and weights and increased total CD4+ T cells and CD8+ T cells, including IFNγ+ CD8+ T cells and GZMB+ CD8+ T cells." (PMID 39256398, 2024). "Research findings suggest that HLA-DR+ CD4+ T lymphocytes play a critical role as activated T cells in anti-tumor immune responses." (PMID 38933268, 2024). "Following depletion of either CD4+ or CD8+ T cells in SFB-colonized, B16-3340 tumor-bearing mice, there was a significant loss in the efficacy of anti-PD-1 treatment." (PMID 39185202, 2024). "In mouse, the principal mechanism for increasing CD4+ CD25+ presenting FOXP3+ population in the tumor site is via the conversion of CD4+ CD25- T cells." (PMID 38571964, 2024). "This decrease in CD4+T cells is likely to lead to a significant reduction in the tumor-eliminating effect, consequently facilitating the tumor cells evasion from the primary site." (PMID 38263363, 2024). "Composition analysis indicated that CD8 T cells, resting memory CD4 T cells, M0 macrophages and M2 macrophages were generally overrepresented in 12 tumours." (PMID 38130025, 2024). "To explore which immune populations mediate tumor rejection, we injected immunodepleting antibodies against either CD4+ and CD8+ T cells or NK cells into C57BL/6 mice bearing either T cell–inflamed EV or Mgat5-KO tumor cells (2838c3)." (PMID 38912584, 2024). "Further regulation of tumor invasion was explored after inclusion, with BMMSCs in the collagen gel, of CD4+-enriched T-cells from DLN of tumor-immunized mice." (PMID 38540350, 2024). "The immune checkpoint therapy upregulated the transcription factor DEC1 in tumor antigen-specific CD8+ and CD4+ T cells, while DEC1 deficiency inhibited immune checkpoint therapy-induced macrophage transformation from M2 to M1 subtype." (PMID 38807374, 2024).